IRF3 (interferon regulatory factor 3)
Diseases named in the same sentence as IRF3 in open-access papers (continued):
Sharing a sentence is not in itself a finding about the gene and the disease.
liver disease (5 papers, 2021 to 2022). "Dysregulation of IRF3 functions is associated with viral, inflammatory, and hepatic diseases." (PMID 36507301, 2022). "Recent studies have revealed a key role for IRF3 activation in the pathogenesis of chemically-induced liver disease." (PMID 34591933, 2021). "We evaluated the effect of auranofin in an in vitro cell culture model of liver disease, in which IRF3 plays a critical role." (PMID 34619149, 2021). "All three of these inducers contribute to liver injury, implicating IRF3 in the development of liver disease pathology." (PMID 33805458, 2021). "Since IRF3-mediated apoptosis is also detrimental in liver diseases, we investigated the effect of auranofin on fatty-acid-induced cell death." (PMID 34619149, 2021). "IRF3-mediated hepatocyte cell death contributes to alcoholic and nonalcoholic, liver diseases." (PMID 34619149, 2021). "Thus, either mechanism of IRF3-mediated apoptosis could be important for HAV induced liver disease." (PMID 34591933, 2021). "IRF3 mediates pathology independently of downstream IFN signaling, as Ifnar1-/- mice are not protected against ethanol-related liver injury or HAV-induced liver disease." (PMID 34591933, 2021). "Mavs-/- and Irf3-/-Irf7-/- mice, both of which lack the signaling downstream of RLRs required for virus-induced IFN synthesis, are just as permissive for infection as Ifnar1-/- mice, but they do not develop liver disease when infected with HAV." (PMID 34591933, 2021).
lung disease (5 papers, 2018 to 2025). "Together, these data suggest that the systemic autoimmunity and lung disease caused by the loss of PARP7 activity is driven by IRF3 transcriptional activity." (PMID 39969510, 2025). "Irf3−/− or Irf3S1/S1 (transcription defective) or Sting−/− rescues Parp7H532A/H532A mouse autoimmunity and lung disease." (PMID 39969510, 2025). "Mice deficient in Parp7 or carrying an enzymatic-dead mutant Parp7 developed systemic autoimmunity and lung disease driven by IRF3 transcriptional activity." (PMID 39969510, 2025). "Multiple innate sensing pathways likely lead to tonic IRF3 activation in peripheral tissues that are amplified by PARP7 deficiency, although our data suggest that STING is a key driver for lung disease." (PMID 39969510, 2025). "Evidence from genetic experiments in mice demonstrates that STING-associated lung diseases are independent of IRF3 but rely on T cells." (PMID 37036972, 2023). "For instance, STING-associated lung disease due to a gain of function mutation in the protein (N153S) is T cell dependent but does not require IRF3/IRF7 or IFNAR." (PMID 33488589, 2020). "Interestingly, when crossed to mice deficient in IRF3 (preventing the production of IFNβ via STING) the mice still developed dysregulation of immune cells and lung disease." (PMID 30038614, 2018).
psoriasis (5 papers, 2017 to 2025). An autoimmune condition characterized by red, well-delineated plaques with silvery scales that are usually on the extensor surfaces and scalp. "IRF3, a member of the IRF family, is implicated in the STING-IRF3 pathway, suggesting potential improvements in psoriasis treatment through its inhibition." (PMID 38289616, 2024). "Activation of IRF‐3/7 leads to type I interferon production and IFN‐α produced mainly by pDCs, contributing to initiate psoriasis." (PMID 28377495, 2017).
reovirus infection (5 papers, 2011 to 2024). "Interferon-β promoter stimulator-1 and IRF-3 were shown to be required for efficient apoptosis following reovirus infection, suggesting a common mechanism of antiviral cytokine induction and activation of the cell death response." (PMID 21245912, 2011). "Furthermore, we examined the phosphorylation of IRF3 and NF-κB subunit p65 in WT, PARP9 KO, MAVS KO, and PARP9/MAVS DKO BMDC after reovirus infection." (PMID 33976210, 2021). "We further analyzed the proteomic data of in vivo reovirus infections and, interestingly, found that classical reovirus and NDRV infections significantly upregulated the expression of RIG-I, MDA5, IRF3, and several ISGs, such as Mx, viperin, IFIT5, and IFITM2 in both the liver and spleen." (PMID 33344524, 2020). "As important negative controls, in the absence of reovirus infection, CHX or GuHCl did not by themselves cause notable induction of IRF3 phosphorylation." (PMID 32956403, 2020). "Specifically, knock-out or knock-down of RIG-I was sufficient to eliminate IRF3 phosphorylation and expression of IFNs and ISGs during reovirus infection yet did not decrease the first round of replication for either T3D strains." (PMID 32956403, 2020).
steatosis (5 papers, 2015 to 2026). Increased lipid within the cytoplasm of cells. "In mice on an HFD diet, systemic knockdown of IRF3 prevented steatosis and glycemic abnormalities, while hepatocyte-specific knockdown of IRF3 only impacted glycemic abnormalities." (PMID 38999981, 2024). "Irf3-/- mice are protected against liver injury following binge exposure to ethanol, whereas Irf3S1/S1 mice with transcriptionally-incompetent IRF3 develop steatosis, ALT elevation and inflammatory cytokine expression." (PMID 34591933, 2021).
type 2 diabetes (5 papers, 2018 to 2025). "One of these genes is Interferon-Response Factor 3 (IRF3), the expression of which is positively associated with insulin sensitivity and negatively associated with type 2 diabetes in human adipose tissue." (PMID 35682832, 2022). "Here, we show that IRF3 expression in human adipose tissues is positively associated with insulin sensitivity and negatively associated with type 2 diabetes." (PMID 34091599, 2021). "Furthermore, IRF3−/− mice develop obesity, insulin resistance, glucose intolerance, and finally, type 2 diabetes due to an increase in proinflammatory macrophages (M1) and the concomitant loss of IL-10 in adipose tissue." (PMID 35682832, 2022). "Moreover, IRF3 has been found to activate hepatic injury through the STING-IRF3 pathway, trigger endothelial inflammation induced by free fatty acids, and participate in β-cell lipotoxicity in type 2 diabetes." (PMID 40083324, 2025).
Alzheimer disease (4 papers, 2022 to 2025). A progressive, neurodegenerative disease characterized by loss of function and death of nerve cells in several areas of the brain leading to loss of cognitive function such as memory and language. "However, a study has suggested that stimulation of the STING/IRF3 pathway induces a reduction in neuroinflammation in a transgenic mouse model of Alzheimer’s disease." (PMID 35936778, 2022). "Moreover, by downregulating the expression of TLR signaling components and their downstream NF-κB effectors and interferon regulatory factor 3 (IRF-3), cumin essential oil increases inflammation processes in the Alzheimer’s disease model." (PMID 37760822, 2023).
colon cancer (4 papers, 2013 to 2025). "The expression of IRF3 in patients with colon cancer was negatively correlated with the infiltration level of B cells, CD8+ T cells, and macrophages, and positively correlated with the infiltration of CD4+ T cells." (PMID 34488791, 2021). "In colon cancer, a deubiquitinating enzyme USP4 suppressed anti-tumor immune responses by deubiquitinating TRAF6 and IRF3, hindering the nuclear localization of the latter protein and thus inhibiting cellular interferon responses and antigen presentation." (PMID 40183093, 2025). "Our data have demonstrated that IFNγ enhanced IRF3/7 expression and upregulation of IRF7 increases the expression of IFI35 in both murine colon cancer cells." (PMID 37380972, 2023).
depression (4 papers, 2021 to 2024). "In PD model mice, 1‐methyl‐4‐phenyl‐1,2,3,6‐tetrahydropyridine (MPTP) has been shown to induce depression‐like behavior, and this is accompanied by an increase in the expression levels of STING and IRF3 in the hippocampus." (PMID 38525112, 2024).
endotoxemia (4 papers, 2012 to 2025). "Lipopolysaccharide (LPS), an endotoxin derived from gram-negative bacteria, promotes the secretion of proinflammatory cytokines and mediates endotoxemia through activation of mitogen activated protein kinases, NF-κB, and interferon regulatory factor-3." (PMID 24573134, 2014). "LPS/TLR4 signaling triggers NF-κB and interferon regulatory factor 3 (IRF3) activation, further amplified by ROS generated through nicotinamide adenine dinucleotide phosphate (NADPH) oxidase, thereby tightly linking endotoxemia, oxidative stress, and inflammation in ALD." (PMID 41462685, 2025).
esophageal cancer (4 papers, 2021 to 2025). A primary or metastatic malignant neoplasm involving the esophagus. "During JEV infection suppression of PTEN promotes phosphorylation of AKT and IRF-3 at 24 h post infection in human microglial cells The role of the hsa-miR-21-5p in regulation of PTEN/PI3K/AKT pathway has also been reported in oesophageal cancer." (PMID 34233673, 2021). "In addition, overexpression of IRF2 promotes esophageal cancer cell proliferation and mutations of SNPs in genes such as IRF3, IRF5, and IRF7 may facilitate the progress of esophageal cancers, while IRF4 may be regarded as a protective factor in ESCC." (PMID 39384770, 2024).
latent infection (4 papers, 2017 to 2025). "IRF3, a central transcription factor downstream of STING, has been shown to play a pivotal role in HCMV sensing and innate immune signalling, yet little is known about how latent infection modulates IRF3 translocation or activity." (PMID 40872823, 2025). "The activation of the STING pathway upstream of p-IRF3 during latent infection in CD34+ cells suggests the activation of DNA sensors." (PMID 40872823, 2025). "UL138 inhibits the pathway downstream of STING but upstream of interferon regulatory factor 3 (IRF3) phosphorylation and NF-κB function and reduces the accumulation of interferon beta mRNA during both lytic and latent infections." (PMID 34903048, 2021). "However, given the involvement of both STAT1 and IRF-3 in multiple signaling pathways, the role of T cell-intrinsic IFN signaling in supporting latent infection of germinal center B cells needs to be specifically defined." (PMID 35968944, 2022).
liver cancer (4 papers, 2020 to 2025). An epithelial or non-epithelial malignant neoplasm that arises from the liver. "The expression of PTEN can directly increase the activation of IRF-3, promote the nuclear transcription of IRF-3, thus affecting the synthesis of interferons, and influence the occurrence and development of liver cancer." (PMID 35022030, 2022). "To investigate the role of IL-33 in HBV+DEN-induced liver cancer, we subjected Il33 knockout (Il33KO), ST2 knockout (ST2KO), and Il33 transcription factor, Irf3, knockout (Irf3KO) mice to HBV+DEN liver carcinogenesis protocol." (PMID 40579434, 2025).
neuroblastoma (4 papers, 2017 to 2023). Neuroblastoma (NB) is the most common solid, extracranial childhood tumor. "IFN‐β treatment has been shown to downregulate the PI3K/Akt pathway in neuroblastoma cells, and it is conceivable that IRF3‐induced p‐AKT inhibition is mediated through the IFN‐β/PI3K pathway." (PMID 35088922, 2022). "This might also be due to the impaired signaling of IRF3, which is the main transcription factor of triffosome, as neuroblastoma 22L-N2a58 cells overexpressing IRF3 showed a decreased level of structurally abnormal prion protein (PrPSc)." (PMID 35979366, 2022).
pancreatic cancer (4 papers, 2012 to 2025). "Tropisetron effectively inhibits IL-33 expression by blocking the phosphorylation of IRF3, which helps reduce the risk of chronic pancreatitis and pancreatic cancer in mice with potential implications for humans." (PMID 40647388, 2025). "The IRF3-IL-33 axis is highly active in chronic pancreatitis and its associated pancreatic cancer in humans." (PMID 38816352, 2024). "IRF3-IL-33 axis was highly active in chronic pancreatitis and its associated pancreatic cancer in humans." (PMID 36711701, 2023). "Our study reveals that tropisetron, a 5-HT3 receptor antagonist, blocks IL-33 expression by inhibiting IRF3 activation and effectively reduces chronic pancreatitis and prevents pancreatic cancer." (PMID 40647388, 2025). "There was a significant impairment of dsRNA-induced IRF3 DNA binding activity in human embryonic kidney and pancreatic cancer cells with C10 treatment." (PMID 23090018, 2012). "Targeting the IRF3 pathway and IL-33 expression with safe small molecules may provide innovative therapeutic strategies to tackle inflammation-driven pancreatic cancer." (PMID 40647388, 2025). "Expression of IL33 and other IRF3 target genes, TNF, IL1B, and CXCL10, were highly upregulated in pancreatic cancer compared to the normal pancreas in a large collection of samples represented in TCGA and GTEx databases." (PMID 38816352, 2024).
sarcoma (4 papers, 2016 to 2025). A usually aggressive malignant neoplasm of the soft tissue or bone. "Furthermore, the IRF3/STAT1 pathway was reported to be associated with M2 polarization in a murine model of sarcoma." (PMID 35967424, 2022). "Here, we showed that the perpetuation of DNA damage leads to the accumulation of cytosolic dsDNA, triggering the cGAS-STING pathway, activating the transcription factor IRF3, and eventually promoting IFNβ production in surviving sarcoma cells." (PMID 40986050, 2025). "Furthermore, we determined in a syngeneic sarcoma mouse model that radiation up-regulates IRF3, IFNβ, and the T cell chemokines CCL2 and CCL5 in the tumor microenvironment, which are associated with activation and increased infiltration of Th1/Tc1 T cells in the tumor microenvironment." (PMID 27014915, 2016). "We showed that IRF3 specifically binds to the POU5F1 promoter region and directly stimulates gene transcription in response to cGAS-STING pathway activation in sarcoma cells." (PMID 40986050, 2025). "Analysis of our RNA-Seq data revealed that no major pathway components, including Cgas, Sting, Irf3, or Tbk1, were downregulated in Atrx-deleted mouse sarcomas relative to their Atrx WT control either in vitro or in vivo." (PMID 37200088, 2023).
SARS-CoV infection (4 papers, 2010 to 2023). "The need for IFN antagonists to reach a threshold level before becoming effective is illustrated by the observation that at an early time point during SARS-CoV infection, IRF3 is observed to translocate to the nucleus whereas it is excluded from the nucleus at a later time point." (PMID 23658627, 2013). "Unfortunately, the TRANSFAC database that we used in this study to identify enriched TFs did not contain data on IRF-3 or its regulatory binding sites, preventing us from deducing whether IRF-3 activation was induced in 2B4 cells upon SARS-CoV infection." (PMID 20090954, 2010). "SARS-CoV infection in vitro failed to activate interferon regulatory factor 3 (IRF3) which is responsible for producing type 1 interferon." (PMID 36914565, 2023).
small cell lung carcinoma (4 papers, 2021 to 2024). Small cell lung cancer (SCLC) is a highly aggressive malignant neoplasm, accounting for 10-15% of lung cancer cases, characterized byrapid growth, and early metastasis. "hnRNPA1 regulates alternative splicing of interferon regulatory factor 3 and affects immunomodulatory functions in human non–small cell lung cancer cells." (PMID 33573689, 2021). "A recent study found that DNA damage response (DDR) inhibitors are sufficient to induce an anti-tumor immune response in small cell lung cancer, which is mediated by the STING-TANK binding kinase 1 (TBK1)-IFN regulatory factor 3 (IRF3) pathway." (PMID 35978045, 2022). "This current work is in direct contrast to previously published work demonstrating that Chk1 inhibition in small cell lung cancer cells increased TBK1 and IRF3 phosphorylation, CCL5, IFN-β and CXCL10 mRNA expression, and elevated PD-L1 expression all indicative of a type I IFN response." (PMID 35006469, 2021).
allergic reaction (3 papers, 2019 to 2023). "At first, we analyzed the association of IRF3 in mast-cell-associated allergic disease using an anti-DNP-IgE/DNP-HSA-induced PCA mouse model." (PMID 37296614, 2023). "Among them, IRF3 contributes to the regulation of the adaptive immune response and is associated with inflammatory conditions and allergic diseases." (PMID 37296614, 2023). "In this study, we newly demonstrated the functional importance of IRF3 in mast-cell-mediated allergic disease and revealed the action mechanism of IRF3 in the granule content production by IgE/Ag-induced mast cell activation." (PMID 37296614, 2023). "It is verified that the alteration of IRF3 expression regulates HDC processing, the release of granule contents, such as histamine, β-hexosaminidase, and cytokines, and consequently, an allergic reaction." (PMID 37296614, 2023).
Arthritis (3 papers, 2016 to 2021). Inflammation of a joint. "In M2-polarizing conditions, a pro-M1 and pro-angiogenic upstream regulator Irf3, and the pro-M1 pro-arthritis upstream regulator Irf7, and NF-κB were all predicted to be activated by 65–79*SE, and reciprocally inhibited by 65–79*PE." (PMID 33510427, 2021). "Mosquitoes fed on blood meals of 7.5 (but not 5.9) log10CCID50/ml were able efficiently to transmit virus to adult C57BL/6 and IRF3/7-/- mice, with the latter mice showing overt signs of arthritis post-infection." (PMID 27760560, 2016).
brain infarction (3 papers, 2022 to 2025). Tissue necrosis in any area of the brain, including the cerebral hemispheres, the cerebellum, and the brain stem. "Pharmacological inhibitors such as C‐176 and H151 effectively diminish brain infarction, edema, and neuronal injury by attenuating the activation of downstream signaling molecules like IRF3 and NF‐κB, which are pivotal for M1 microglial responses." (PMID 40242160, 2025).
Encephalopathy (3 papers, 2023 to 2025). Encephalopathy is a term that means brain disease, damage, or malfunction. "We showed that CBD significantly reduces the transcript levels of the proinflammatory immune biomarkers IL‐12, CD68, CCL2, and IRF3, found previously upregulated in rodent models of induced epilepsy and in pediatric patients with encephalopathy." (PMID 40608247, 2025).
endothelial dysfunction (3 papers, 2022 to 2025). In vascular diseases, endothelial dysfunction is a systemic pathological state of the endothelium (the inner lining of blood vessels) and can be broadly defined as an imbalance between vasodilating and vasoconstricting substances produced by (or acting on) the endothelium. "Interestingly, an increase in p-IRF3 levels, the downstream target of cGAS and STING, was observed predominantly in the intima, which is consistent with our hypothesis that aging induces the endothelial dysfunction of blood vessels via the cGAS-STING pathway." (PMID 36465181, 2022).
heart failure (3 papers, 2018 to 2026). Inability of the heart to pump blood at an adequate rate to meet tissue metabolic requirements. "Transcript levels of selected markers of heart failure that are also targets of IRF3 and NF-κB transcription factors were quantified by reverse transcription PCR (RT-PCR) in cardiac RNA extracts from the control and experimental mice." (PMID 40608429, 2025).
hepatitis C virus infection (3 papers, 2016 to 2025). A viral infection caused by the hepatitis C virus. "TRIM27 inhibits the type I IFN response against hepatitis C virus infection by inhibiting the IRF3 and NF-κB pathways." (PMID 40251491, 2025). "Finally 6 genes (NCOR2, NR1H3, PPARA, IRF3, MAP2K3, and TLR6) were enriched in 3 immune-related pathways, including toll-like receptor signaling pathway, EB virus infection, and hepatitis C." (PMID 37845378, 2023).
herpesvirus infection (3 papers, 2008 to 2026). "Constitutively expressed in the cytosol, IRF3 is phosphorylated during herpesvirus infection and translocated into the nucleus to target the IFNβ promoter." (PMID 18331636, 2008).